MMP7 (matrix metallopeptidase 7)
Diseases named in the same sentence as MMP7 in open-access papers (continued):
Sharing a sentence is not in itself a finding about the gene and the disease.
gastric cancer (continued). "The mentioned meta-analysis did not include follow up survival data and did not address the inconsistency in results of studies that have investigated prognostic effect of MMP7 in gastric cancer." (PMID 25919283, 2014). "Accordingly, we found different results for prognostic effect of tissue and serum MMP7 level in gastric cancer." (PMID 25919283, 2014). "A similar role of MMP7 in vessel invasion and metastasis is reported by studying the expression and tissue localization in human gastric carcinoma." (PMID 24143235, 2013). "We noticed that isoproterenol stimulation significantly up-regulated MMP-7 expression at both mRNA and protein levels in gastric cancer cells." (PMID 20939893, 2010). "The present study demonstrates that G17-induced migration and MMP7 promoter induction in gastric cancer cells involve an inhibition of GSK3β pathway." (PMID 20637111, 2010). "Accumulated lines of evidence show that MMP-7 is involved in the invasion and metastases of gastric cancer." (PMID 20939893, 2010). "Semi-quantitative and real-time PCR analyses showed that MMP-7 expression at transcriptional level was low in gastric cancer cell lines." (PMID 20939893, 2010). "To further investigate the role of MMP-7 and β2-AR in the metastasis of gastric cancer, we analyzed the expression MMP-7 and β-ARs in the cancerous, peri-cancerous and metastatic tissues from a patient with gastric cancer." (PMID 20939893, 2010). "An understanding of how MMP-7 gene is up-regulated under stress will help to elucidate the mechanisms of MMP-7 overexpression in gastric cancer, especially at an early stage." (PMID 20939893, 2010). "The expression of MMP-7 in gastric cancer tissues was found to be at the site where β2-AR was overexpressed and the levels of MMP-7 and β2-AR were the highest in the metastatic locus of gastric cancer." (PMID 20939893, 2010). "In the present study, we investigated the effects of catecholamine stimulation on MMP-7 expression in gastric cancer cells and elucidated the molecular mechanisms of the up-regulation of MMP-7 level by catecholamine through an adrenergic signaling pathway." (PMID 20939893, 2010). "Up-regulation of MMP-7 expression through β2-AR-mediated signaling pathway is involved in invasion and metastasis of gastric cancer." (PMID 20939893, 2010). "In the present study, we identified increased MMP-7 expression in the gastric cancer cell lines in response to the stimulation of stress-related hormone catecholamine." (PMID 20939893, 2010). "MMP-7 has been recognized as an important mediator of cancer progression and considered as an independent prognostic marker for primary gastric cancer." (PMID 20939893, 2010). "To study the correlation of β2-AR level with MMP-7 expression in human gastric cancer, we collected five gastric cancer tissue samples and analyzed the expression of β2-AR and MMP-7 by immunohistochemical labeling." (PMID 20939893, 2010). "Increased MMP-7 expression was identified at both mRNA and protein levels in the gastric cancer cells in response to isoproterenol stimulation." (PMID 20939893, 2010). "This experiment provides in vitro evidence to confirm that STAT3 and c-Jun, under catecholamine stimulation, can physically interact and bind to the AP-1 site to achieve transactivation of MMP-7 gene in gastric cancer cells." (PMID 20939893, 2010). "MMP7 is known to mediate migration of gastric cancer cells, the transcription of which was induced by G17." (PMID 20637111, 2010). "The overexpression of MMP-7 is frequently identified in premalignant gastric lesions and most gastric carcinomas." (PMID 20939893, 2010). "Taken together, all the lines of evidence suggest a prevalence of SFRP5 downregulation in gastric cancer, which is responsible for the upregulation of the expression of MMP-7 and MT1-MMP." (PMID 19586554, 2009).
gastric cancer (continued). "Three of these are known to be involved in gastric cancer: MMP7, SPARC, and SOD2, and the other four have no such reported associations (INHBA, IGFBP7, NEK6, and LUM)." (PMID 18827816, 2008). "Many markers, including CEA, CK20, CK19, MAGE, and MMP-7, have previously been applied to detect micrometastases of gastric cancer." (PMID 17667927, 2007). "To corroborate these observations, we now assessed MMP-2 and MMP-9 with new techniques in an expanded group of gastric cancer patients (n=81) and included for comparison MMP-7, MMP-8 and the tissue inhibitors of MMPs, TIMP-1 and -2." (PMID 16538217, 2006). "Matrix metalloproteinase-7 was selected because MMP-7 production in various types of carcinomas has predominantly been found in tumour cells and because MMP-7 was recently suggested as potential marker for gastric carcinoma." (PMID 16538217, 2006). "MMP-7 expression was found in 283 of 400 (70.75%) gastric cancer tissues." (PMID 35496040, 2022). "Furthermore, MMP-3 and MMP-7 were strongly elevated in the serum of patients with H. pylori–positive gastric cancer in comparison to the both gastritis groups." (PMID 35163805, 2022). "Metastasis in gastric cancer was substantially related to MMP-7 upregulation." (PMID 35163805, 2022). "Thus, concomitantly increased serum levels of MMP-3 and MMP-7 seem to be more relevant for gastric dysplasia and gastric cancer." (PMID 35163805, 2022). "Additionally in gastric cancer, the participation of Rcan2 in tumor progression has been associated with EGFR, nuclear β-catenin, MMP7, laminin-γ2, and VEGF." (PMID 36267816, 2022). "Elevated MMP-7 levels have been reported in multiple types of cancers, including gastric cancer." (PMID 35496040, 2022). "The findings support the hypothesis that MMP-7 expression has a crucial role in the progression and prognosis of gastric cancer." (PMID 35496040, 2022). "Similarly, H. pylori significantly upregulates vimentin in the gastric cancer cell lines as well as increases the expression of MMP-7." (PMID 34827233, 2021). "The results revealed that exosomal AGT, SERPINH1 and MMP7 may serve as biomarkers for gastric cancer diagnosis and prognosis and involved in GC progression." (PMID 34215253, 2021). "In summary, HEYL, MMP7, THBS1, and KRT17 are not only highly expressed in gastric cancer, but also associated with poor prognosis and may be potential prognostic biomarkers." (PMID 34157940, 2021). "CDH3, LEF1, and MMP7 can be used as candidate biomarkers to construct a neural network model from hub genes, which may be helpful for the early diagnosis of gastric cancer." (PMID 34485109, 2021). "In our study, LEF1 was found to predict gastric cancer jointly with CDH3 and MMP7, which may be used as a diagnostic marker for gastric cancer in the future." (PMID 34485109, 2021). "All these results indicate that MMP7 is a very important biomarker for gastric cancer." (PMID 34485109, 2021). "SPARC suppresses angiogenesis by downregulating the expression of VEGF and MMP-7 in gastric cancer." (PMID 32226513, 2020). "Levels of MMP-7 might correlate with the degree of rehabilitation after treatment and poor prognosis in gastric cancer survival." (PMID 32340207, 2020). "Although our results suggested that expression of MMP-7 or TIMP-1 alone cannot serve as an indicator for patient prognosis, there was a significant association between coexpression of MMP-7 and TIMP-1 with poor survival of patients with gastric carcinoma." (PMID 33005257, 2020). "In gastric cancer, MMP7 was previously identified to be overexpressed, and Koskensalo and co-workers suggested that this gene may be an independent prognostic marker." (PMID 29484116, 2018). "Restoration of MMP-7 can increase invasive activity of gastric cancer." (PMID 29358963, 2017). "The authors speculated that the observed mTOR independent MMP-7 expression was attributable to the complex regulation of mucosal inflammation in the tissue microenvironment in gastric cancer." (PMID 28634370, 2017).
gastric cancer (continued). "Therefore, MMP-7 can be a useful biomarker for determining the progression of gastric cancer and prognosis." (PMID 28512631, 2017). "In addition, AP-1 has shown its pivotal roles in inducing MMP-7 expression in human gastric cancer cells." (PMID 25823818, 2015). "uPA and MMP-7 may then degrade the extracellular matrix in order to promote tumor invasion, thereby contributing to gastric cancer invasiveness." (PMID 25997455, 2015). "Interestingly, recent studies have emphasized the importance of MMP7 in gastric cancer progression, since MMP7 has potential to not only degrade the extracellular matrix but also confer an anti-apoptotic effect on cancer cells." (PMID 25925261, 2015). "Although the summary estimates for association between tumor tissue MMP7 and prognosis of gastric cancer was significant, the pooled HR of two studies that used serum MMP7 was not statistically significant." (PMID 25919283, 2014). "Subgroup meta-analysis results for MMP7 impact on Gastric Cancer survival." (PMID 25919283, 2014). "It introduces MMP7 as a potential target for molecular anti-cancer therapy in gastric cancer." (PMID 25919283, 2014). "Extracted prognostic effect of MMP7 in gastric cancer merits notice from two clinical aspects." (PMID 25919283, 2014). "In summary, the growth inhibition of gastric cancer by SPARC seems to be mediated through its suppression effects on MMP-7 and VEGF expressions, which may in turn inhibit microvessel infiltration into tumours." (PMID 22957090, 2012). "However, the possible molecular mechanisms of MMP-7 overexpression in gastric cancer are still largely unexplored." (PMID 20939893, 2010). "STAT3 and c-Jun could physically interact and bind to the AP-1 site, implicating that the interplay of both transcriptional factors on the AP-1 site is responsible for isoproterenol-stimulated MMP-7 expression in gastric cancer cells." (PMID 20939893, 2010). "In the present study, we investigated the effects of catecholamine stimulation on MMP-7 expression in gastric cancer cell lines and elucidated the molecular mechanisms of the up-regulation of MMP-7 level by catecholamine through an adrenergic signaling pathway." (PMID 20939893, 2010). "In order to investigate whether catecholamine associates with the expression of MMP-7 in gastric cancer cells, we first inspected the effects of β-AR agonist isoproterenol on the transcription of MMP-7 gene in gastric cancer cell lines HGC-27 and MGC-803." (PMID 20939893, 2010). "The main findings of this study strongly support the hypothesis that up-regulation of MMP-7 expression through β2-AR-mediated signaling pathway is involved in invasion and metastasis of gastric cancer." (PMID 20939893, 2010). "In addition, SOX12 can promote gastric cancer metastasis by up‐regulating MMP7 and IGF1." (PMID 41425852, 2025). "MMP7 expression was significantly associated with poor clinicopathological features of gastric cancer patients, including vascular invasion, undifferentiated histological types, higher TNM stage, and high CEA levels, and was considered one of the prognostic markers of gastric cancer." (PMID 36467074, 2022). "Hence, we aimed to determine whether MMP-7 expression can be used as a prognostic biomarker in gastric cancer patients." (PMID 35496040, 2022). "This suggests that MMP-7 might be a potential candidate marker for identifying patients who have more aggressive gastric cancer and suggests its potential usefulness to clinicians in selecting better therapeutic approaches and conducting intensive follow-up of these patients." (PMID 35496040, 2022). "The mechanism may be that MMP-7 can cleave E-cadherin in gastric cancer cells." (PMID 34157940, 2021). "For example, in gastric cancer, the MMP1 and MMP2 increased expression is related to the loss of E-cadherin expression, thereby, leading cancer proferliation and metastasis.MMP-3 and MMP-7 have association with the development of Helicobacter pylori-related gastric cancer." (PMID 34422902, 2021).
gastric cancer (continued). "In summary, an association between the presence of MMP2 and MMP7 proteins and (p-)mTOR expression in gastric cancer could not be confirmed." (PMID 26652716, 2015). "Therefore, in this study, we hypothesized that SPARC might modulate proliferation and angiogenesis by regulating VEGF and MMP-7 expressions in gastric cancer cells." (PMID 22957090, 2012). "Interestingly, STAT3 and c-Jun were found to bind to the single AP-1 site in MMP-7 promoter simultaneously, implicating that the interplay of both transcriptional factors at one binding site is responsible for isoproterenol-stimulated MMP-7 expression in gastric cancer cells." (PMID 20939893, 2010). "In concentrations below 10 μM, EA effectively suppressed MMP-7 and MMP-9 expression triggered by acidity, restraining the migratory and matrigel-infiltrating capacity of gastric cancer cells." (PMID 38002335, 2023). "In the gastric cancer patients in our sample, the frequency of high MMP-7 expression was significantly higher than the frequency of low MMP-7 expression." (PMID 35496040, 2022). "SOX12 transcriptionally targets matrix metallopeptidase 7 (MMP7) and insulin-like growth factor 1 (IGF1) to facilitate gastric cancer metastasis." (PMID 35485164, 2022). "Second, some patients received chemotherapy after surgery, resulting in a greater chance of survival for those patients than for those who did not receive chemotherapy; therefore, an association between MMP-7 expression and the survival time of gastric cancer patients could not be demonstrated." (PMID 35496040, 2022). "In gastric cancer cells, H. pylori–induced expression of MMP-3 and MMP-7 led to the downregulation of E-cadherin and accelerated cellular migration and invasion." (PMID 35163805, 2022). "A western blotting experiment was carried out, and the results showed that the relative expression levels of MMP7, CDH3, and LEF1 in gastric cancer tissues were increased compared with the control group." (PMID 34485109, 2021). "Immunohistochemical results showed that the expression level of MMP7, CDH3, and LEF1 in gastric cancer tissues was higher than in the control group." (PMID 34485109, 2021). "This low dose of ellagic acid reduced acidity-promoted expression of MMP7 and MMP9 and inhibited the migrating and matrigel-infiltrating capability of gastric cancer cells, indicating the inhibitory action of ellagic acid against acidity-enhanced invasiveness." (PMID 31835645, 2019). "We herein identified a large number of genes associated with the ECM and cell adhesion to be differentially expressed in intestinal gastric cancer, including TIMP1, MMP7, FN1, SPARC, LUM and BGN, which were upregulated." (PMID 29484116, 2018). "MMP-2, MMP-7, and MMP-14 are members of matrix metalloproteinase family, which play an important role in gastric cancer invasion and migration." (PMID 29358963, 2017). "Researchers have widely studied p-mTOR, pS6, p4EBP1, PTEN, MMP7, and DCN expression in human solid cancer tissues, including gastric cancer." (PMID 25909163, 2015). "Protein expression levels of pAMPKα, p-mTOR, pS6, p4EBP1, MMP7, DCN and PTEN were analyzed in 39 resected primary gastric cancer samples." (PMID 25909163, 2015). "MMP7 and CD44, both β-catenin downstream genes, were involved in macrophage-activated gastric cancer cell invasion." (PMID 26226629, 2015). "In the current work, we found that TGR5 activation inhibited MMP2, MMP7 and MMP14 gene expression in gastric cancer cells." (PMID 26417930, 2015). "The mechanism of UPK1A in gastric carcinoma remains to be fully explored, and therefore our future studies will focus on this mechanism and the relationship between UPK1A and MMP7 in GCs." (PMID 24698999, 2014). "In this study, we detected those metastasis relevant factors, including MMP7, MMP9 and MMP14, which are particularly important in gastric cancer." (PMID 24386080, 2013). "SPARC suppresses angiogenesis of gastric cancer by down-regulating the expression of VEGF and MMP-7." (PMID 22957090, 2012).
gastric cancer (continued). "In this study, real-time PCR was used to determine mRNA levels of MMP-2, MMP-7, MMP-9 and MT1-MMP in gastric cancers." (PMID 19586554, 2009). "Overexpression of MMPs has been observed in a series of cancers, with that of MMP-2, MMP-7, MMP-9 and MT1-MMP, in particular, typically present in gastric cancer." (PMID 19586554, 2009). "Real-time reverse-transcription PCR was performed to determine the mRNA expression of some members in MMP family, including MMP-2, MMP-7, MMP-9 and MT1-MMP in 32 gastric cancer specimens and corresponding matched normal tissue specimens." (PMID 19586554, 2009). "Our initial finding showed that SFRP5 expression is significantly downregulated in gastric cancer, while the subsequent quantitative real-time PCR analysis revealed that MMP-2, MMP-7, MMP-9 and MT1-MMP are all upregulated in it." (PMID 19586554, 2009). "The results showed that MMP-2, MMP-7, MMP-9 and MT1-MMP were all significantly upregulated in gastric cancer specimens compared to matched normal tissue specimens (For both MMP-2 and MMP-9, P < 0.01; for both MMP-7 and MT1-MMP, P < 0.001)." (PMID 19586554, 2009). "Second, some MMPs, such as MMP-2, MMP-7, MMP-9 and MT1-MMP, are frequenly overexpressed in gastric cancers, primarily in both tumor cells and stromal cells (except MMP-7, which is only expressed in tumor cells)." (PMID 19586554, 2009). "MMP-2 (gelatinase A), MMP-9 (gelatinase B), MMP-7 (matrilysin) and MMP-14 (MT1-MMP) are over-expressed in human gastric cancer." (PMID 12085177, 2002). "Furthermore, a study using a xenograft model with transplanted gastric cancer tissue has revealed that chronic stress stimulates the β-adrenergic receptor (ADRB), which leads to the overexpression of VEGF, MMP-2, MMP-7, and MMP-9 in transplanted tumor tissue." (PMID 40362226, 2025). "Although the prognostic value of MMP-7 in gastric cancer has been widely investigated, there are no ideal markers because the results are not consistent." (PMID 35496040, 2022). "In addition, increased levels of MMP-3, MMP-7 and MMP-11 in serum reflected an advanced stage of gastric cancer and also predicted shorter survival." (PMID 35163805, 2022). "Further studies comparing MMP-7 expression and CEA levels in gastric cancer are needed." (PMID 35496040, 2022). "Although MMP-7 has been suggested as a candidate marker in gastric cancer, the reports are inconsistent, with some studies showing that MMP-7 expression does not correlate with the survival of patients with gastric cancer." (PMID 35496040, 2022). "This study showed that MMP7, CDH3, and LEF1 are highly expressed in gastric cancer tissues." (PMID 34485109, 2021). "The result demonstrated that MMP7, CDH3, and LEF1 might be identified as biomarkers for gastric cancer." (PMID 34485109, 2021). "It was finally confirmed that HEYL, MMP7, THBS1, and KRT17 may be potential biomarkers of gastric cancer." (PMID 34157940, 2021). "This study shows that MMP7, CDH3, and LEF1 are highly expressed in gastric cancer tissues." (PMID 34485109, 2021). "Chemerin promoted the growth and invasion of gastric cancer cells by inducing the phosphorylation of p38 MAPK and the expression of IL-6, vascular endothelial growth factor (VEGF), and matrix metalloproteinase-7 (MMP-7)." (PMID 31781638, 2019). "The upregulation of HSF1 in gastric cancer cells stimulates the expression of MMP2, MMP7 and MMP9." (PMID 30326922, 2018). "Grhl2 reduces the expression of MMP-2, MMP-7 and MMP-9, which may partly explain the inhibitory effect of Grhl2 on invasion and migration of gastric cancer." (PMID 28067907, 2017).